CCL2 (C-C motif chemokine ligand 2)
Diseases named in the same sentence as CCL2 in open-access papers (continued):
Sharing a sentence is not in itself a finding about the gene and the disease.
melanoma (continued). "An additional study reports a significant expression change of six chemokines (namely, CCL2, CCL3, CCL4, CCL5, CXCL9, and CXCL10) related to the lymphocyte infiltration in the melanoma tissue." (PMID 33302400, 2020). "In a recent study it was shown that, tumor derived factors such as colony stimulating factor-1 (CSF-1), CCL-2, IL-34, and VEGF recruit circulating macrophages to the melanomas." (PMID 31134198, 2019). "Researchers used modified melanoma-condition (MCM) to differentiate human monocytes to macrophages and they found that these MCM-induced macrophages strikingly increased CCL2 expression." (PMID 30800130, 2019). "CCL2 has been reported to bind CCR4 on cytotoxic T lymphocytes, resulting in their recruitment to melanoma cells thus implicating an immune-mediated protective role in cancer." (PMID 26885690, 2016). "A murine melanoma (B16) and a lung carcinoma cell line (LLC) appear to have delayed upregulation of CCL2 and CCL5 transcript levels." (PMID 27852031, 2016). "CCL2 has been shown to regulate expression of IL-6 expression in lung fibroblasts and VEGF in melanoma cells." (PMID 27283985, 2016). "By showing that down-regulation of CCL2-driven signals by SAHA and temozolomide via JNK contributes to reduce melanoma growth, we provide a rationale for the therapeutic advantage of the drug combination." (PMID 24980831, 2014). "MCP-1 (or CCL2) and RANTES (or CCL5) increased the infiltration of TAM into primary tumors, including breast and ovarian carcinomas, melanoma, and glioblastoma." (PMID 20490273, 2010). "It was discerned that within Flu treated B16-F10 melanoma sites, there were no alteration in the levels of CCL2, CCL3, and CCL5, which are pivotal in mediating neutrophil recruitment." (PMID 40226609, 2025). "In ESCA, the CCL2-CCR2 axis drives TAM infiltration and M2 polarization, suppressing CD8+ T cells and promoting immune evasion—a pattern mirrored in melanoma, non-small cell lung cancer (NSCLC), and colorectal cancer (CRC), where CCL2 blockade synergizes with immune checkpoint inhibitors (ICIs)." (PMID 40134607, 2025). "Moreover, their inhibition led to a reduction in key pro-inflammatory cyto-chemokines genes, such as CCL2, IL6, and CXCL8, regulated by NFkB-mediated transcription and contributing to melanoma cell survival and to immunosuppressive TME." (PMID 41550951, 2025). "Melanoma responds to this pro-inflammatory response by releasing suppressive mediators including CSF1, TGF-β, and CCL2, which reprogram micro-glial cells to become trophic, anti-inflammatory cells characterized by increased expression of Arg1, IL-10, and PD-L1." (PMID 41463339, 2025). "The combination of pharmacologic sEH inhibition and immune checkpoint blockade resulted in decreased gene expression of the pro-inflammatory cytokines Il-6, Cxcl1, Tnfα, Ccl2, and Ccl4 compared to control after 11 d of treatment in the B16F10 melanoma tumor tissue." (PMID 38330013, 2024). "In this study, all 30 melanoma cell lines tested expressed CCL2, whereas normal melanocytes did not, and CCL2 expression was required for the melanoma cells to form tumors in SCID mice." (PMID 38786066, 2024). "SNAI1+ melanoma cells display enhanced production of TGF-β, thrombospondin-1 (TSP1), CCL2, and lipocalin 2 (LCN2), which may have additional immunosuppressive effects beyond Treg and DC regulation." (PMID 38426087, 2024). "Dedifferentiated melanoma cells have been reported to secrete multiple cytokines in greater quantity, notably CCL2, CCL5 and IL-1β, either without inflammatory stimuli or when stimulated with TNFα." (PMID 39736644, 2024). "CCL2 stimulated the invasion ability of naïve melanoma cell in organs (not treated with any drugs or exposed to therapy), and both occurrences jointly promoted melanoma tumor formation and metastasis activities." (PMID 37174106, 2023).
melanoma (continued). "Though Nivolumab did not significantly alter serum cytokine profiles, in melanoma patients we observed a deviation from the physiological range for 7 out 18 cytokines tested: IL-1β, IL-6, CCL2, CXCL8, VEGF, IL-5 and IL-13." (PMID 35173725, 2022). "Because the addition of T cells to melanoma cultures inhibits expression of CD206, we hypothesize that EGF expression may also be limited, resulting in decreased CCL2 levels and inhibited myeloid chemotaxis to sites." (PMID 35265066, 2022). "Interestingly, a subset of SASP components, including cytokines CCL2, CCL3, CXCL12, cathepsin CTSD, or the protease inhibitor SERPINE1, are secreted in a RAB27A‐dependent manner in senescent melanoma cells." (PMID 36087066, 2022). "Additionally, we performed in vitro experiments to evaluate the effects of gabapentin on the proliferation of the melanoma cell line B16–BL6/Zs green, CCL2 secretion, and calcium influx." (PMID 34575835, 2021). "Moreover, as demonstrated for melanoma cells, IL-1β, COX-2 and CCL2 were upregulated in bcl-2 overexpressing H1299 cells, while IL-8 was not affected and IL-17 was undetectable." (PMID 32269145, 2020). "The general level of CCL2/MCP-1 is affected by cycling hypoxia that also increases the expression of this chemokine, as shown by research on alveolar macrophages, THP-1 monocytes, endothelial cells, and melanoma cells." (PMID 32781743, 2020). "In particular, melanoma cells expressing high levels of bcl-2 displayed enhanced activation of the IL-1β/COX-2 axis, which paralleled an increased gene expression and secretion of IL-8, IL-17 and CCL2." (PMID 32269145, 2020). "We showed that treatment with melanoma-derived exosomes or miR-125b-5p overexpression induced a morphological switch of M1 macrophages together with an enforced expression of IL-1β, CCL-1, CCL2, and CD80 (B7-1)." (PMID 32079286, 2020). "Melanomas developed from cells lacking MyD88 showed an enhanced secretion of chemoattractant ligands such as CCL2, CXCL10 and CXCL1 and have an improved infiltration of macrophages to the tumor site." (PMID 28662055, 2017). "CCL2 is detectable in several types of tumors and was previously detected in human melanoma cell lines, but CCL2 was not previously reported in melanoma cells from tumor specimens." (PMID 26684239, 2016). "Our results demonstrate that CCL2 and IL6, which are present in the SSMC, also promote an activation of STAT3 and that STAT3 silencing prevents the acquisition of the mesenchymal, stemness and melanoma-initiating phenotypes." (PMID 24344100, 2013). "Lipopolysaccharides can stimulate normal human melanocytes to produce IL-1β, TNFα, IL-6, IL-8, CCL2, CCl3, and CCL5, and chemotherapy of melanoma-bearing mice results in enhanced expression of CCL5 and the CXCR3 ligands CXCL9, CXCL10, and CXCl11 by tumor cells." (PMID 22745913, 2012). "A group has investigated the use of a dominant negative CCL2 construct lacking 2-8 amino acids at its N-terminus (7ND) targeting CCR2 in a melanoma mouse model." (PMID 21943176, 2011). "The consequences of the introduction of CCL2 into biologically early, nontumorigenic melanoma cells were found to depend on the level of CCL2 secretion." (PMID 15900302, 2005). "In a melanoma model, HIF−1α inhibition was also shown to increase the accumulation of natural killer (NK) cells and CTLs in the tumor bed by upregulating chemokines such as CCL2 and CCL5, thereby enhancing the effectiveness of anti−PD−1 therapy and peptide vaccines." (PMID 40297580, 2025). "We found that the antitumor effect of IMQ was strongly diminished in c-JunΔ/ΔMx1-Cre mice, c-JunΔ/ΔCD11c-Cre mice and Ccl2−/− mice; however, the lack of c-Jun or Ccl2 did not have a significant impact on the growth of orthotopic B16-F10 melanomas in untreated control mice." (PMID 39849091, 2025). "The prognostic role of CCL2 in melanoma has not been revealed yet." (PMID 36747118, 2023).
melanoma (continued). "TAMs account for up to 30% of the melanoma tumor content and are polarized to an M2-like, immunosuppressive phenotype by melanoma cell-derived factors including but not limited to the B-cell lymphoma 2 protein, acidosis, colony-stimulating factor 1, CXCL12 and CCL2." (PMID 40838054, 2023). "Recent reports show a “bidirectional communication” between melanoma cells and adipocytes, especially in obese patients, consisting of the secretion of high amounts of pro-inflammatory factors such as IL-6, IL-11, TNF-α, monocyte chemoattractant protein (MCP)-1/CCL2, and PAI-1 by the excessive fat." (PMID 35334544, 2022). "First, high level and activity of AhR mediates the invasive/dedifferentiated phenotype of melanoma through the direct regulation of the expression of many genes involved in invasion (COL1A1, COL6A1, COL6A2, CYR61, STC2...) and dedifferentiation phenotypes (CCL2, NTM, NUAK2, SOX9, ABCG2...)." (PMID 36305167, 2022). "However, in line with elevated CCL2 levels, we found increased recruitment of CD45+ leukocytes to endothelial cells, which had been stimulated with a conditioned medium harvested from CHI3L1-treated melanoma cells." (PMID 33920100, 2021). "Notably, miR-146a upregulation with concomitant increased COX2, PDL1, VEGFA, CCL2, IL6, IL8 and MCL1 expression characterized the MDSCs induced in vitro by melanoma extracellular vesicles from monocytes from healthy donors, suggesting cell type-specific regulation of the miR-146a/COX2 axis." (PMID 32967672, 2020). "In addition, among the genes indirectly regulated by miR-146a through NFkB activity, we found CCL2, IL6, and VEGFA, which contribute to the proinflammatory phenotype, CD274 (PDL1), which promotes melanoma cell proliferation, and BCL2L1 and MCL1 antiapoptotic genes." (PMID 32967672, 2020). "In addition, CCL2 has been shown to recruit MDSC, which are able to inhibit CD8+ T cell entry into the tumor microenvironment and subsequent anti-tumor response in mouse models of melanoma." (PMID 30126117, 2018). "Here, we describe the molecular correlates of the efficacy of the combination of SAHA and TMZ, and we propose that disruption of CCL2-driven signals by SAHA and TMZ may impair survival of human melanoma cells resulting in a synergistic drug interaction which in mice results in delayed disease onset." (PMID 24980831, 2014). "Combined with absence of p16/Arf tumor suppressors, the level of H-rasG12V may thus control key factors determining differentiation (Brn2, Mitf), EMT (JNK, Smad3, TGFβ signaling) and Ccl2 production (MAPK, JNK) during melanoma development as discussed hereafter." (PMID 23173060, 2012). "In addition, our study allows the identification of an immunosuppressive signature characterized by high GLI and low cytokine/chemokine expression (CCL7, CCL2, CCL20, CXCL8, CXCL1 and CXCL10), which could be used to stratify melanoma patients with poor survival." (PMID 39090759, 2024). "Furthermore, fibroblasts activated by melanoma cells showed upregulation of the MMPs’ expression mediators’ levels (pERK, p-p38, CD44, RUNX), enhanced secretion of lactate, several cytokines (IL8, IL6, CXCL1, CCL2, ICAM1), and proteins related to angiogenesis (GM-CSF, DPPIV, VEGFA, PIGF)." (PMID 35538545, 2022). "Additionally, the long noncoding RNA LINC00330 binds CCL2 to suppress TAM reprogramming, a regulatory interaction not yet reported in melanoma or NSCLC." (PMID 40134607, 2025).
Stroke (222 papers, 2008 to 2026). Sudden impairment of blood flow to a part of the brain due to occlusion or rupture of an artery to the brain. "Given that Cxcl10 and Ccl2 have both been associated with stroke prognosis in humans, their increased expression in old mice compared with that in young mice is noteworthy." (PMID 40867143, 2025). "Based on observations in traumatic brain injury, epilepsy, tumors, AD and stroke, CCL2 is also implicated in neuroinflammation." (PMID 39272984, 2024). "High plasma CCL2 concentrations have been shown to be associated with increased long-term risk of stroke, while CCL2 signaling pathways have been shown to be responsible for ischemic stroke progression and atrial fibrillation." (PMID 34356595, 2021). "C–C motif chemokine ligand 2 (CCL2) is associated with neurological repair after stroke and delivery of various cells into the brain via CCL2/CCR2 (CCL2 receptor) interaction." (PMID 33096826, 2020). "Overexpression of CCL2 in experimental stroke models observed increased infarct volume and greater ischemia, while CCL2 deficient mice had less tissue damage after permanent middle cerebral artery occlusion." (PMID 33278887, 2020). "A recent report indicated that CCL2 is associated with neurological repair after stroke and delivery of various cells into the brain via CCL2/CCR2 interaction." (PMID 33096826, 2020). "CCL2 has been implicated in stroke models to promote the motility of adult neural progenitor cells and enhancing their differentiation into neurons." (PMID 24802239, 2014). "Importantly, genetic deletion of the astrocyte-specific CCL2 restored vessel coverage by astrocytes and the number of vessel-associated astrocytes in Slc4a4-icKO mice after stroke." (PMID 38709635, 2024). "After stroke, deletion of astrocytic CCL2 rescued several phenotypes by Slc4a4 loss, including infarct size, BBB leakage, increased CD31 intensity, impaired tight-junctional marker expression (Claudin-5), and enhanced transcellular transport (pCav-1, Cav-1) surrounding the peri-lesion region." (PMID 38709635, 2024). "Additionally, the secretion of CCL2 and IL-8 by monocytes critically depends on P-selectin, with CCL2 expression linked to stroke severity." (PMID 39022737, 2024). "Furthermore, CCL2 deficiency has been shown to decrease macrophage infiltration to the infarct core after stroke." (PMID 37378751, 2024). "Notably, analysis of 341 DE mRNA associated with stroke (259 upregulated, 82 downregulated) in the IR group revealed upregulation of genes like Ccl2, Cxcl1, C3, Serpine1, Adamts7, Csf3, Ptx3, MMP8, Lif, and Lcn2, and downregulation of Gdf10, Agtr2 and Shank3." (PMID 39170713, 2024). "In experimental permanent stroke models, CCL2 deficiency leads to a decrease in the number of monocytes recruited to the ischemic lesion and as a consequence the mice develop smaller infarct volumes post-stroke." (PMID 33918875, 2021). "Importantly, a genetic polymorphism in the CCL2 gene was associated with stroke and HbF variability in SCD." (PMID 33003401, 2020). "Of note, MCP-1/CCL2 was recently identified as biomarker of stroke risk in a large meta-analysis." (PMID 33319833, 2020). "Furthermore, research by our group and others have reported alterations in the inflammatory cytokine response and tissue damage in Ccl2-deficient mice after TBI or stroke, prior to the onset of leukocyte infiltration." (PMID 20942978, 2010). "Additionally, sequence variations in the promoter regions of CCL19 and CCL21 have been associated with an increased susceptibility to myocardial infarction, while genetic predisposition to elevated circulating levels of CCL2 correlates with a heightened risk of stroke." (PMID 40236901, 2025). "Moreover, circulating CCL2 levels appear genetically influenced; higher levels are linked to a greater risk of stroke, suggesting that CCL2-targeted therapies might reduce stroke incidence." (PMID 39850880, 2024).
Stroke (continued). "Clinical studies have reported a correlation between CCL2 expression levels and poststroke outcomes, highlighting its relevance in human stroke pathology." (PMID 40867143, 2025). "After stroke, CCL2/CCR2 induces microglial recruitment, increases leukocyte infiltration and the expression of inflammatory mediators, further aggravates damage to the BBB, and leads to brain edema and neuronal death." (PMID 40289984, 2025). "While previous studies have reported the induction of Cxcl10 and Ccl2 in stroke, the age-dependent enhancement of their induction is a novel finding of our study." (PMID 40867143, 2025). "Both IL6 and CCL2 lose rhythmicity in response to clock disruption resulting in the generation of pro-inflammatory macrophages, which increase the severity of stroke 45,47,48." (PMID 38169640, 2024). "An important role for CCL2 has been confirmed in various diseases including multiple sclerosis, stroke, Alzheimer’s disease, acute brain injury and experimental autoimmune encephalitis." (PMID 39839349, 2024). "Previous studies have shown that Ccl2 levels are highly increased in the brain after stroke and that silencing the Ccl2 gene is protective in stroke models, promoting repair." (PMID 37378751, 2024). "In our dataset, pericytes residing in the ipsilateral stroke region showed highly upregulated levels of Ccl2 compared to the other cells in the brain." (PMID 37378751, 2024). "Mice of the different genotypes were evaluated for functional consequences of stroke, infarct volume, activation of glia cells, and for QC, isoQC and CCL2 expression." (PMID 39272984, 2024). "Like pan-NOS inhibition, the iNOS inhibitor restores exacerbated BBB dysfunction and astrocytic CCL2 production in Slc4a4-icKO mice after stroke." (PMID 38709635, 2024). "CCL2 is known to be induced in the brain by multiple events with an inflammatory component, including stroke." (PMID 39272984, 2024). "At 24 h post-stroke, CCL2 and IL-6 were significantly upregulated following a single dose of HFI419." (PMID 37957163, 2023). "CCL2 mediates monocyte migration from the bone marrow into the bloodstream by binding to CCR2, whose expression is associated with stroke severity." (PMID 37452512, 2023). "Following stroke, chemokines CXCL1and CCL2 levels are elevated in liver, which lead to an increase in neutrophils and monocytes and an excessive inflammatory response, resulting in the release of ALT from necrotic hepatocytes." (PMID 37808495, 2023). "The monocyte chemoattractant protein-1 (MCP1/CCL2) was upregulated in the penumbra with IRAP inhibitor treatment following stroke." (PMID 37957163, 2023). "For instance, interference with early-response pathways such as CCL2 are often investigated acutely after stroke within the first 24 h." (PMID 37337154, 2023). "Animal studies and clinical trials have shown that CCL2/CCR2 mediate the pathological process of ischemic stroke, and a higher CCL2 level in serum is associated with a higher risk of any form of stroke." (PMID 35408846, 2022). "CCL1 and CCL2 serve as early chemoattractants in stroke lesions, encouraging the infiltration by immune cells." (PMID 35912857, 2022). "Genetically predicted levels of CCL2, also known as MCP-1, relate to a higher coronary artery disease and stroke risk, as shown in a recent mendelian randomization study." (PMID 36555579, 2022). "Overexpressed CCL2 has been shown to increase macrophage infiltration and cerebral infarction area, indicating that CCL2 can promote inflammatory response and impede recovery post-stroke." (PMID 36742051, 2022). "For example, astrocytes are the primary source of CCL2 in adult stroke models, while damaged neurons are the primary source of CCL2 in neonatal hypoxia/ischemia models." (PMID 36211352, 2022). "In combination with other inflammatory cytokines, elevated CCL2 can also increase the severity of neurodegeneration, cognitive dysfunction, and stroke." (PMID 35464491, 2022).